NCOR1P1 (NCOR1 pseudogene 1)
Synonyms: bB329D4.2; formerly C20orf191
Gene: Transcribed unprocessed pseudogene on chromosome 20 (26,103,489 to 26,113,986, reverse strand). Ensembl gene ENSG00000240108.
Diseases named in the same sentence as NCOR1P1 in open-access papers:
NCOR1P1 is named in the same sentence as 1 disease in open-access papers, as found by Europe PMC text mining. Sharing a sentence is not in itself a finding about the gene and the disease. The quoted sentences say what the papers report.
cancer (1 paper, 2024). A tumor composed of atypical neoplastic, often pleomorphic cells that invade other tissues. "However, there are no previous reports of sex specificity or survival specificity for NCOR1P1 in ccRCC or other cancers." (PMID 38982123, 2024).